MCL1 (MCL1 apoptosis regulator, BCL2 family member)
Diseases named in the same sentence as MCL1 in open-access papers (continued):
Sharing a sentence is not in itself a finding about the gene and the disease.
tumor (continued). "miR-153 is an ancient and conserved miRNA which suppresses the tumor development by downregulating tumor-associated genes, such as SNAI1, KLF5, and MCL-1." (PMID 29959560, 2018). "FBXW7 acts as a tumor suppressor involved in the ubiquitination and degradation by the proteasome of substrates with oncogenic activity, including MCL-1." (PMID 29805751, 2018). "It has been described that activated MNK1 promotes the onset of tumor development which was attributed to the ability of MNK1 to enhance the expression of the anti-apoptotic protein MCL1." (PMID 29568373, 2018). "Surprisingly, immunohistochemical analysis revealed that both WT and HOM tumours expressed equally high levels of MCL-1, whereas a range of MCL-1 expression was observed in early mammary lesions in the HOM mice." (PMID 29339815, 2018). "Therapeutic targeting or genetic deletion of MCL-1 is sufficient to delay tumour development and regress established tumours in vivo." (PMID 30405205, 2018). "The combination of ABT-263 with MCL1 si-NPs increased tumor cell killing and diminished tumor cell growth in each LTED cell line tested." (PMID 29343814, 2018). "Accordingly, miR-204 suppresses tumor cell growth, apoptosis and survival by targeting Mcl-1, Bcl-2 and TrkB, impacted tumor migration, invasion and metastasis by targeting FOXC1 and slug." (PMID 28388577, 2017). "Use of selective inhibitors of BCL-2, BCL-XL, and MCL-1 allowed us to examine the relative dependence of these proteins on pro-survival activity of the PDX tumor cells." (PMID 28848242, 2017). "The expression of STAT3 downstream genes (cyclin D1 and Mcl-1) was also detected by real-time quantitative PCR, and samples from Atn-treated mice showed downregulated cyclin D1 and Mcl-1 mRNA expression levels compared with tumor tissues from vehicle mice." (PMID 27861147, 2017). "Theoretically, the anti-tumor activity of ABT-263 can be enhanced by increasing Bim protein expression or reducing Mcl-1 expression." (PMID 29156797, 2017). "We found that metformin decreased HCC tumor burden, and tumor tissues showed elevated apoptosis with reduced Mcl-1 and phosphorylated 4E-BP1 protein levels." (PMID 28881582, 2017). "Diverse anti-apoptotic proteins as Bcl-XL, Bcl-2, Bcl-w, and Mcl-1 can prevent cell death in tumor cells." (PMID 28352231, 2017). "Mcl-1 and cyclin D are tumor-promoting genes that play essential roles in tumor progression, metastasis and resistance." (PMID 27926520, 2017). "The outcomes of this study also shed light on understanding Mcl-1 in ESCC tumor development and suggest that Mcl-1 can be a target for preventing ESCC development." (PMID 29383093, 2017). "While clinical inhibition of BCL-2 has been achieved with the BH3 mimetic venetoclax, anti-tumor efficacy is limited by compensatory induction of MCL-1." (PMID 29269870, 2017). "As previous study, Mcl1 contributes to tumorigenesis, particularly in solid cancers, and second generation Mcl1 antagonists are actively being sought, distinguishing it as a potentially important molecular marker of tumor progress." (PMID 29152113, 2017). "The difference of MCL-1 overexpression between the tumor and the normal groups was statistically significant." (PMID 28659182, 2017). "Studies have shown that distinct signaling pathways are involved in the activation of Mcl-1 gene expression in different tumor cells, including mitogen-activated protein kinase (MAPK), phosphatidylinositol 3-kinase (PI-3K) and JAK/STAT signal." (PMID 29383093, 2017). "Inhibition of SPHK2 attenuated tumor growth by induction of caspase 3-mediated cell apoptosis via enhancing the degradation of anti-apoptotic protein Mcl-1, and increasing the expression of a pro-apoptotic protein Noxa." (PMID 29145490, 2017). "MCL-1 frequently overexpressed in a variety of human tumor tissues, including stomach, liver, pancreas, prostate and lung, which contributes to tumor development and progression and associated with poor patient prognosis." (PMID 28659182, 2017).
tumor (continued). "The significant degradation of Mcl-1 in tumor tissue showed the consistent characteristic with that of Mcl-1 in vitro assay." (PMID 28881661, 2017). "Collectively, our data suggest that dinaciclib will probably have single-agent anti-tumour activity against a subset of SCLC that either carry c-MYC amplification or are MCL-1-addicted." (PMID 28714472, 2017). "This compound was shown to be very specific for Mcl-1, well-tolerated by animal models and efficient at triggering cell death in Mcl-1-dependent tumor cells." (PMID 28516063, 2017). "Inhibiting USP9X using the small molecule WP1130 triggers tumor cell apoptosis, potentially by decreasing the MCL-1 protein level." (PMID 28101374, 2017). "The anti-apoptotic (Bcl-2, Bcl-w, Bcl-xL, and Mcl1) and pro-apoptotic (Bax, Bad, Bok, Bak) Bcl-2 family proteins can affect tumor metastasis through regulation of the mitochondrial apoptotic pathway." (PMID 29190919, 2017). "ABT-263 (Navitoclax) is a novel oral inhibitor for Bcl-2 family proteins, acting as a Bcl-2 homology 3 (BH3) mimetic, and leading to apoptosis, except in tumor cells with Mcl-1 overexpression." (PMID 28352231, 2017). "Mcl-1 function indeed depends on cellularcontext and its knockdown can even increase sensitivity to apoptosis triggered by theextrinsic route in tumor cells." (PMID 28845295, 2017). "FBXW7 is a key regulator of tumor malignant potential, and its substrate MCL1 regulates therapeutic resistance in human malignancies." (PMID 29348852, 2017). "The up-regulation of Mcl-1 results in resisting cell death, increasing cell proliferation, and tumor cell survival." (PMID 29254209, 2017). "The aim of current study is to develop novel strategies to efficiently kill ESCC tumor cells by utilizing recently developed Mcl-1 inhibitor A-1210477 that directly activate the cell death pathway." (PMID 29383093, 2017). "In view of the roles of MCL-1 in tumorigenesis, tumor progress and chemoresistance, the combinations of MCL-1 inhibitors with classical cytoxic agents have been actively investigated." (PMID 28659182, 2017). "S63845 binds with high affinity to the BH3‐binding groove of MCL1, and selectively induced apoptosis of MCL1‐dependent tumour cells in a BAK/BAX‐dependent manner with ~ 1000‐fold greater potency than A‐1210477." (PMID 28548464, 2017). "These tumours display increased sensitivity to DNA‐damaging agents and are dependent on high levels of MCL1 for their survival suggesting a potential therapeutic vulnerability of HUWE1‐mutated tumours." (PMID 28003334, 2017). "Although the key-role of MCL-1 or BCL-2 in tumor cell survival and drug resistance is undisputed, little is known about the relevance of related BCL2A1/A1 (called BFL-1 in humans), a poorly investigated member of the BCL-2 family." (PMID 27694901, 2017). "We found that silencing PVT1 reduced xenograft tumor growth, which was partially rescued by Mcl-1 overexpression." (PMID 29254209, 2017). "In this study, we detected MCL1 copy number variation in TMA from ESCC tumor tissues in a Chinese population, additionally, conducted survival analyses to analyze prognostic values of MCL1 copy number gain on survival." (PMID 29152113, 2017). "We previously demonstrated that OC ascites protect tumor cells from apoptosis through activation of Akt and Erk signaling resulting in the upregulation of anti-apoptotic proteins Mcl-1 and cFLIP." (PMID 27613122, 2016). "Inhibition of Jak2 by G6 inhibits MCL1 via downstream inhibition of its transcription factors and therefore contributes further to enhancing induction of apoptosis and reducing tumor cell viability." (PMID 27056884, 2016). "The siRNA markedly reduced the levels of MCL-1 protein in these cells, resulting in a significant reduction in soft agar colony forming ability (P<0.05) and tumor growth in vivo." (PMID 27846237, 2016).
tumor (continued). "For Mcl-1, this finding was further verified by an immunohistochemical staining, comparing expression levels in both mucosa and tumor tissue derived from Bcl-xLIEC-KO and control mice and on the mRNA level by qRT-PCR analysis." (PMID 27537525, 2016). "In contrast, MCL-1 antagonism had limited effects on MCL-1 low MDA-MB-231-2A cells when grown as monolayers in vitro but delayed tumor onset in mice bearing MDA-MB-231-2A xenografts." (PMID 27931239, 2016). "One of these is the modulation of glycolytic metabolism, which regulates Bcl-2 family members expression, especially Mcl-1, but also sensitizes tumor cells to apoptosis through the modulation of the main energy sensor of the cell, the AMPK/mTOR pathway." (PMID 27689327, 2016). "Previous studies have suggested that deubiquitinase USP9X stabilizes myeloid cell leukemia sequence 1 (MCL1) and promotes tumor cell survival and apoptosis resistance." (PMID 27783990, 2016). "Overexpression of Mcl-1 has been found to be an indicator of tumor progression and poor outcomes in numerous human tumors." (PMID 27517746, 2016). "Consistent with the notion that miR-130a can act as a tumor suppressor by targeting BCL2 and MCL-1 expression, lower expression of miR-130a is associated with poor prognosis as indicated by shorter overall survival and treatment-free survival in CML patients." (PMID 27179712, 2016). "The anti-apoptotic genes BCL2, MCL1 and A20 are regulated in tumour cells by imiquimod, allowing the onset of apoptotic pathways." (PMID 27936237, 2016). "Noteably, some Bim is now found bound to Mcl-1 in the recurrent tumor, alluding to the potential for evolution of Mcl-1 dependent clone in the tumor if ABT-199 treatments are given for a longer duration of time." (PMID 26874859, 2016). "We established that a partial reduction of caloric intake by 25% represents an efficient way to decrease Mcl-1 expression in tumor cells." (PMID 27689327, 2016). "Our own and other studies show that blocking the effects of Mcl-1 is a promising approach to slow tumor growth, induce apoptosis, and overcome drug resistance in BC cells, and Her2-positive BC cells in particular." (PMID 26921175, 2016). "Taken together, our results demonstrate that the loss of two tumor suppressors (miR-32 and ARF) in concert with overexpression of oncogenic MCL-1 represent key complementary drivers in melanomagenesis." (PMID 27846237, 2016). "PEITC and/or CDDP-mediated changes in Mcl-1 protein level in the tumor tissue were generally in agreement with the molecular alteration observed in cultured cells." (PMID 26848531, 2016). "Somatic CNVs in BCL2L1 and MCL1 genes were tested in tumor tissues from 516 NSCLC patients in southern China; afterward, survival analyses were conducted with overall survival (OS) as outcome." (PMID 27264345, 2016). "Taken together, Mcl-1 targeting strategies in MM are not only important for direct anti-tumor effects but also modulate the BM microenvironment including MDSC to enhance the host immune response." (PMID 25871384, 2015). "FBXW7 is considered an haploinsufficient tumor suppressor that targets several proto-oncoproteins for degradation, including cyclin E, Myc, c-jun, Mcl1." (PMID 25885523, 2015). "Despite the confirmed importance of Mcl-1 in several neoplasms, the role of Mcl-1 in OSCC survival has yet to be explored." (PMID 26009874, 2015). "Consistent with its frequent amplification, MCL1 is highly expressed in many tumor types, and high expression levels of MCL1 contribute to tumor development and resistance to chemotherapy." (PMID 25909780, 2015). "Thiazolides not only induce neutralization of Bcl-xL and Mcl-1, but also promote Mcl-1 degradation, which likely further lowers the apoptosis resistance of tumor cells." (PMID 26043078, 2015). "pSTAT3 as well as Mcl-1 were upregulated in CD11b+ cells derived from tumor-bearing mice compared to those from naïve mice." (PMID 25871384, 2015).
tumor (continued). "Each tumor cell has often developed its own characteristic dependency on specific protein kinases that antagonizes Bim expression, while fortifying Mcl-1 expression." (PMID 26405162, 2015). "Cyclin E knock-down restored ABT-737 sensitivity to acquired and inherently resistant Mcl-1-dependent tumor cells." (PMID 26219338, 2015). "Many chemotherapeutic drugs induce apoptosis through downregulation of Mcl-1 expression in tumor cells to reach their therapeutic effects." (PMID 25729215, 2015). "Mcl-1 is highly expressed in a variety of human tumor tissues, such as breast cancer, colon cancer, lung cancer, ovarian cancer, prostate cancer, kidney cancer, and liver cancer." (PMID 26078955, 2015). "Targeting cyclin E using Cdk inhibition, alone or in combination with the BH3 mimetics ABT-737 or ABT-199 substantially reduces survival of Mcl-1-dependent tumor cells." (PMID 26219338, 2015). "The average tumor volume of the mice that were treated with Mcl-1 siRNA alone at the end of the experiment was 875 ± 134.3 mm3, which was significantly lower than that of control and vemurafenib treated mice." (PMID 26497853, 2015). "In a PANC-1 xenograft mouse model, we demonstrated that the combination of metformin and aspirin significantly inhibited tumor growth and downregulated the protein expression of Mcl-1 and Bcl-2 in tumors." (PMID 26056043, 2015). "CaP tumor samples from patients often overexpress specific Bcl-2 family member proteins, especially Mcl-1 and Bcl-xL." (PMID 25926554, 2015). "MCL1 protein expression was repressed by 65% upon miR-3151 over-expression, thereby testifying the tumor suppressor function of miR-3151 in CLL." (PMID 26517243, 2015). "Several anti-apoptotic proteins, such as Survivin and members of the Bcl family (Bcl-xl, Bcl-2 and Mcl-1) which are known to be crucial for tumor cell survival, are direct target genes of STAT3 and are down-regulated as a consequence of STAT3 inhibition." (PMID 26474284, 2015). "Although tumor cells harbored high levels of Mcl-1 and low levels of Beclin 1 – a relationship inversely found in normal cells – a more detailed understanding of how Usp9X regulates both apoptosis and autophagy is necessary." (PMID 26008975, 2015). "This suggests that during the initial senescence induction or during the latter stages of tumor escape, apoptosis is a fail-safe mechanism that is inactivated by Bcl-xL and/or Mcl-1." (PMID 26485768, 2015). "In a PANC-1 xenograft mouse model, we further demonstrated that the combination of metformin and aspirin significantly inhibited tumor growth and downregulated the protein expression of Mcl-1 and Bcl-2 in tumors." (PMID 26056043, 2015). "MCL-1 is known as a tumor survival factor via suppressing the apoptosis by inhibiting the normal function of proapoptotic Bcl-2 family proteins such as Noxa." (PMID 26526790, 2015). "Inhibition of AXL reversed chemoresistance by decreasing expression of the anti-apoptotic proteins BCL-2, BCL-XL, MCL1 and survivin in tumor cells and activated pro-apoptotic proteins BAD, BAX, BCL-2, BAK and PUMA." (PMID 26328272, 2015). "The expression of MCL-1 mRNA was significantly increased in 77.2% (17/22) of tumor tissues, and the protein level was overexpressed in all three TNBC cell lines." (PMID 26036638, 2015). "The weight of the tumor in Mcl-1 siRNA treated group was reduced by 40% as compared to control and 43% as compared to vemurafenib treated group." (PMID 26497853, 2015). "One of the mechanisms by which rapamycin sensitizes tumor cells is through downregulation of Mcl-1 with simultaneous upregulation of Bim." (PMID 26405162, 2015). "Previous studies have suggested that miR-29b exerts its tumor-suppressing function by targeting oncogenes such as Bcl-2, Mcl-1, and MMP-2." (PMID 26512921, 2015). "We confirmed also the down-regulation of miR-29a in ALK+ ALCL cell lines, which was recently shown to upregulate the antiapoptotic protein MCL1 contributing to tumor cell survival." (PMID 25688981, 2015).
tumor (continued). "USP9X depletion increases poly-ubiquitylation of MCL1, enhances its turnover and sensitises tumour cell lines to the pro-apoptotic drug ABT-737 (a BCL2 antagonist that does not target MCL1)." (PMID 25672900, 2015). "In vivo, vemurafenib resistant A375 xenografts implanted in athymic nude mice showed substantial tumor growth inhibition when treated with a combination of vemurafenib and Mcl-1 inhibitor or siRNA." (PMID 26497853, 2015). "Consistent with our in vitro findings, dinaciclib-induced apoptosis was observed only in the four MCL1:BCL-xL mRNA high ratio tumor models." (PMID 25289887, 2014). "Mutational inactivation of E3 ligase FBW7 was found to occur in several neoplastic diseases, which can decrease Mcl-1 degradation, resulting in increased Mcl-1 protein levels and resistance to chemotherapeutic agents." (PMID 24529193, 2014). "Having been normalized to β-actin for quantification of protein expression, both β-catenin and Mcl-1 exhibited tumor-specific overexpression, with significantly increased level of expression in tumor tissues relative to normal tissues (P <0.001)." (PMID 24947165, 2014). "In order to evaluate the impact of S44563 on the expression of Bcl-2, Bcl-XL, and Mcl-1 proteins, two to four tumor samples have been collected at the time of mice sacrifice for immunohistochemical studies." (PMID 24454684, 2014). "In tumor biology, Mcl-1 plays an oncogenic role by maintaining tumor cell survival through its anti-apoptotic function." (PMID 24947165, 2014). "To further evaluate the association of β-catenin and Mcl-1, we analyzed the expression of both proteins in 31 patients with GIST by western blotting in the tumor specimens and normal counterpart tissues." (PMID 24947165, 2014). "Increased MCL-1 levels are responsible for tumor cell proliferation, migration, self-renewal of CSC and drug resistance to Paclitaxel." (PMID 25153722, 2014). "A genome-wide study of somatic copy number amplification (SCNA) uncovered that MCL1 was enriched in over 3000 tumor samples collected from 26 histological types." (PMID 24564888, 2014). "In contrast, deubiquitinase USP9X, which is overexpressed in some malignancies, stabilizes Mcl-1 and promotes tumor cell survival." (PMID 24529193, 2014). "Bcl-XL suppresses the release of cytochrome c from the mitochondria, survivin interferes with caspase 9 activation in tumor cells and Bcl-XL, Mcl-1 and survivin can antagonize the proapoptotic effect of bax and Diablo in tumor cells." (PMID 24495648, 2014). "Previous studies have shown that Gos downregulated the expression of Bcl-2/Bcl-XL/Mcl-1 proteins in multiple tumor cell lines." (PMID 25231749, 2014). "miR-107 was expressed at a lower level, whereas MCL1 was expressed at a significantly higher level in the tumor tissues when compared with the corresponding normal tissues." (PMID 25386925, 2014). "Mcl-1 is overexpressed in many human tumor specimens, including hepatocellular carcinoma, pancreatic cancer, prostate cancer and others." (PMID 24529193, 2014). "FBW7 (F-box and WD repeat domain-containing 7) or Fbxw7 is a tumor suppressor, which promotes the ubiquitination and subsequent degradation of numerous oncoproteins including Mcl-1, Cyclin E, Notch, c- Jun, and c-Myc." (PMID 24899581, 2014). "NF-κB regulated the expression of Mcl-1, Bcl-2, Bcl-XL, c-IAP1, c-IAP2, FLIP, and survivin, and their overexpression in numerous tumors has been linked to tumor cell survival, chemoresistance, and radioresistance." (PMID 24146961, 2013). "According to Western blotting data, the amount of Mcl1 andpER K1/2 proteins, as well as the tumor cells survival rate, significantlydecreased as compared to the control." (PMID 24303201, 2013). "In combination with NVP-BEZ235 and CDDP, there was dramatic synergy in shrinking tumor volumes and inducing apoptosis through increasing Noxa, Bax and decreasing Mcl-1, Bcl-2." (PMID 23533654, 2013).